NECTIN4 (nectin cell adhesion molecule 4)
Diseases named in the same sentence as NECTIN4 in open-access papers (continued):
Sharing a sentence is not in itself a finding about the gene and the disease.
tumor (continued). "In the primary tumour tissues, high Nectin‐4 expression levels were observed in the Uro (42%, 14/33) and GU (34%, 28/82) subtypes, which are characterised by high expression levels of the luminal genes." (PMID 39801278, 2025). "Amplification of the NECTIN4 gene was also found to be predictive of tumor response to EV and long-term survival for patients with aUC." (PMID 40828887, 2025). "As an IC receptor within the IgSF, TIGIT interacts with ligands such as CD155 (PVR or Nectin-5), CD113 (PVRL3 or Nectin-3), CD112 (PVRL2 or Nectin-2) and PVRL4 (Nectin-4) to suppress T cell activity, facilitating tumour evasion of immune surveillance." (PMID 40994140, 2025). "Nectin‐4 expression was observed in 63% of primary tumours and 87% of LN metastases, with significantly higher levels in LNs." (PMID 39801278, 2025). "Radiolabeled full-length EV antibody was tested exclusively in the model with high nectin-4 expression to compare the tumor uptake and pharmacokinetic profile with those of radiolabeled EV antibody fragments." (PMID 40774696, 2025). "IHC staining revealed high Nectin-4 expression in NCI-N87 and H1975 tumors, while HGC-27 and H520 exhibited minimal staining, supporting the selective expression of Nectin-4 in these tumor tissues." (PMID 40542857, 2025). "NECTIN4-CAR T cells have potent anti-tumor activity even against EV resistant cells, which largely retain NECTIN4 expression, including in a post-EV biopsy cohort." (PMID 40931013, 2025). "A subsequent study reported significantly higher Nectin‐4 gene expression in tumours with consensus luminal subtypes compared to the BA/SQ subtype." (PMID 39801278, 2025). "Nectin-4 expression was detected in 84% of UTUC and 83% of BLCA cases and was associated with papillary morphology, low tumor grade, early pathological T stage, and a favorable prognosis." (PMID 40571752, 2025). "Immunofluorescence staining was performed to assess vascularization (CD31) and nectin-4 expression in tumor and normal tissues." (PMID 40774696, 2025). "In tumor tissues, strong Nectin-4 staining was observed in NCI-N87 and H1975 tumors, consistent with the immunohistochemistry results, while HGC-27 and H520 tumors displayed minimal expression." (PMID 40542857, 2025). "We showed that NECTIN4-CAR T cells exhibit high specificity and potency across a range of UC models, including EV resistant cells, and that NECTIN4-CAR T antitumor activity can be enhanced by short-term priming of tumor cells with TZDs such as rosiglitazone." (PMID 40931013, 2025). "In accordance with these results, we observed higher Nectin‐4 tissue expression in tumours with high luminal protein expression (Uro and GU)." (PMID 39801278, 2025). "These properties allow for precise and noninvasive imaging of Nectin-4 expression, supporting its potential as a valuable tool for stratifying patients and tracking tumor progression in GC and NSCLC." (PMID 40542857, 2025). "In preclinical studies, the nectin-4 and TIGIT interaction inhibited natural killer cell activity, and nectin-4 blocking antibodies enhanced tumor cell killing." (PMID 40225697, 2025). "In PC3-AGS22 cells stably expressing Nectin-4, the biological activity of the mutated ADC was similar to the un-mutated drug, indicating that Mu-anti-Nectin4-VcMMAE retained the targeted anti-tumor activity but ocular toxicity was reduced." (PMID 40507807, 2025). "There was decreased expression of nectin-4 in these metastatic sites compared to their expression on the primary tumor." (PMID 40225697, 2025). "Despite the therapeutic application of EV, only a few studies have investigated Nectin‐4 tissue expression in UBC, and little is known about the spatial distribution of Nectin‐4 within the primary tumour or between primary and metastatic sites." (PMID 39801278, 2025). "Nectin-4 exhibited strong expression in tumor cells, as well as in glandular epithelium and endothelial cells." (PMID 40699695, 2025).
tumor (continued). "For further analyses, we used the central tumour Nectin‐4 expression level when evaluating the results." (PMID 39801278, 2025). "Significantly higher Nectin‐4 expression levels were observed in tumours with MPUC histology (P = 0.002), with 58% (21/36) of these tumours showing high Nectin‐4 expression." (PMID 39801278, 2025). "Systemic rosiglitazone plus NECTIN4-CAR T cells also improved tumor growth inhibition in HT1197 tumor xenografts, without affecting body weight." (PMID 40931013, 2025). "Our findings demonstrate a significantly higher expression of Nectin-4 in tumor cells compared to Nectin-2." (PMID 40699695, 2025). "In many of these malignancies, high levels of Nectin-4 correlate with increased tumor aggressiveness and poorer clinical outcomes." (PMID 40699695, 2025). "We demonstrate significant NECTIN4-CAR T anti-tumor activity in both EV-naïve and EV-resistant settings, and identify a strategy to turn low-expressing tumors into higher-expressing tumors, thereby making them become more susceptible to NECTIN4-CAR T therapy." (PMID 40931013, 2025). "Rosiglitazone administration increased NECTIN4 as well as HPGD (which we used as a surorgate marker of PPARγ activity) in RT112 tumor xenografts." (PMID 40931013, 2025). "For EV, this corresponds to changes in the tumor cell surface expression of nectin-4, processing of the protease-cleavable linker and MMAE in tumor cells, and resistance to the MMAE itself." (PMID 40225697, 2025). "One of the key factors affecting the efficacy of EV is the expression level of Nectin‐4, with previous studies showing that tumours with low Nectin‐4 expression exhibit reduced responses to EV." (PMID 39877564, 2025). "The findings revealed heterogenous expression of both Nectin-2 and Nectin-4 in tumor cells and surrounding stroma, with Nectin-4 expression being significantly higher than Nectin-2 expression." (PMID 40699695, 2025). "BC can be multifocal and exhibits pronounced intra- and intertumoral antigen heterogeneity, including variability in EGFR, Nectin-4 and TROP-2 expression, driven by genetic mutations, altered molecular pathways, and influences of the tumor microenvironment." (PMID 41471825, 2025). "The figure illustrates that Nectin‐4 expression decreases as the tumour progresses from non‐muscle‐invasive to muscle‐invasive disease, and further decreases in metastatic lesions." (PMID 39877564, 2025). "By targeting Nectin-4 on tumor cells and delivering cytotoxic chemicals to promote death, enfortumab vedotin increases the immune-enhancing properties of checkpoint inhibitors, hence generating a synergistic effect with pembrolizumab." (PMID 40387780, 2025). "We found low intra‐tumoral heterogeneity in the primary tumour and significantly higher Nectin‐4 expression levels in metastasis‐bearing LNs." (PMID 39801278, 2025). "Targeting Nectin-4 with the antibody-drug conjugate enfortumab vedotin inhibited tumor growth in multiple patient-derived PDAC organoids." (PMID 41364531, 2025). "In the phase I EV‐101 study, which enrolled metastatic urothelial carcinoma patients with Nectin‐4‐positive tumours, who had previously received ICI therapy, EV demonstrated a superior objective response rate (ORR) of 43%." (PMID 39801278, 2025). "In this context, Nectin-4 is a particularly interesting target, combining high conservation, IC inhibition and tumor specificity." (PMID 40788962, 2025). "Systemic rosiglitazone plus NECTIN4-CAR T cells led to improved RT112 tumor growth inhibition compared to vehicle plus NECTIN4-CAR T cells." (PMID 40931013, 2025). "The expression of Nectin‐4 in various tumours and its impact on patient survival outcomes is currently the subject of active research." (PMID 39801278, 2025). "One of the major challenges is correctly identifying patients who would benefit from EV therapy, as the expression of Nectin-4 at the level of the primary tumour and metastases determines the amount of the drug that can reach tumour cells." (PMID 39858014, 2025).
tumor (continued). "Blocking with an excess of unlabeled EV was done before the injection of radiolabeled EV antibody fragments in the murine tumor models with high and intermediate nectin-4 expression." (PMID 40774696, 2025). "High tumor uptake was delineated in nectin-4–positive xenografts, as shown by small-animal PET/CT imaging at 24–120 h after injection." (PMID 39978811, 2025). "Similar tumor uptake ratios were found for [89Zr]Zr-AGS-22M6 in nectin-4–positive patient-derived xenografts compared with nectin-4–negative patient-derived xenografts." (PMID 39978811, 2025). "After washing out the rosiglitazone, we co-cultured the target tumor cells with NECTIN4-CAR T cells." (PMID 40931013, 2025). "Another study in patients with metastatic urothelial carcinoma who received chemotherapy and ICIs found similar membranous Nectin‐4 expression levels in primary tumours and distant metastases." (PMID 39801278, 2025). "Our strategy of repurposing rosiglitazone to prime NECTIN4 expression across a population of tumor cells with low to moderate expression significantly enhanced anti-tumor activity of NECTIN4-targeting CAR T therapy." (PMID 40931013, 2025). "In all five cases, Nectin‐4 expression decreased as the tumour progressed from non‐muscle‐invasive to muscle‐invasive disease." (PMID 39877564, 2025). "Among 27 available matched primary and metastatic samples, the NECTIN4 copy number variation was stable in 93% of samples, with 7 of 8 NECTIN4-amplified primary tumor tissue samples retaining the amplification in the matched metastatic sample." (PMID 40225697, 2025). "The main objective was to evaluate the expression patterns of Nectin-2 and Nectin-4 within the tumor parenchyma and the surrounding stroma." (PMID 40699695, 2025). "Nectin-4, a cell adhesion molecule, plays a critical role in tumor proliferation, migration, and invasion in many cancers—processes often associated with a poor prognosis." (PMID 39941802, 2025). "This enables accurate, noninvasive visualization of nectin-4 expression and provides a reliable tool for monitoring tumor dynamics." (PMID 40774696, 2025). "The potential for therapeutic exploitation of nectin-4 is particularly promising, with the expression of this protein correlating with patient prognosis in various tumor types." (PMID 40244005, 2025). "Nectin-4 demonstrated strong expression in tumor cells and glandular epithelium, whereas Nectin-2 exhibited overall weaker expression, primarily localized to the surrounding stromal tissue and follicular dendritic cells within secondary lymphoid follicles." (PMID 40699695, 2025). "IHC staining showed that heterogeneity in the expression of both Nectins is found within the tumor itself but that Nectin-4 expression is much stronger." (PMID 40699695, 2025). "Nectin‐4 expression decreased in five out of eight metastatic lesions compared with that in primary tumours." (PMID 39877564, 2025). "Enfortumab vedotin, an antibody-drug conjugate that targets Nectin-4, functions by improving the immune system’s response to tumor cells, whereas pembrolizumab is a PD-1 inhibitor." (PMID 40387780, 2025). "The probe was labeled with [89Zr] for AGS-22M6 (an anti-Nectin-4 mAb) and used for in vivo tumor detection in mice and [18F] for assessing the biodistribution of the probe in crab-eating monkeys." (PMID 38606099, 2024). "This review provides an overview of the role of Nectin-4 in cancers, focusing on clinical trials related to Nectin-4-targeted tumor treatments and the development of novel drugs targeting Nectin-4." (PMID 38606099, 2024). "Immunohistochemical analysis, followed by an evaluation of the H‐score, showed heterogeneous NECTIN‐4 expression pattern across primary tumours and distant metastases, including lymph node, bone and visceral metastases." (PMID 39072867, 2024).
tumor (continued). "Considering that Nectin-4 is weakly to moderately expressed in normal tissues of the skin (cell–cell adhesion role), one of the most EV-related adverse events is skin reactions, with 43.9% of patients reporting rash; among these patients, 14.5% ≥ grade 3." (PMID 39590140, 2024). "Nectin-4 is upregulated in multiple tumor types and promotes tumorigenesis, development, and angiogenesis through pathways such as PI3K/AKT." (PMID 38606099, 2024). "BT7480 targets Nectin-4-expressing tumor cells and then binds to and agonizes CD137 on nearby immune cells to remodel the tumor immune microenvironment, thereby eliminating tumor cells and inhibiting tumor recurrence." (PMID 38606099, 2024). "Specifically, we established HT1376 xenograft tumor models to investigate the impact of autophagy inhibition on the antitumor effect of Nectin-4-MMAE." (PMID 38664366, 2024). "In our investigation, we present novel evidence elucidating the induction of autophagy in nectin-4-positive tumor cells following Nectin-4 ADC exposure." (PMID 38664366, 2024). "Targeted therapies against tumor cells, such as HER2 and Trop-2 for TNBC and Nectin-4 for bladder cancer, can be utilized for targeted tumor cell killing." (PMID 38785789, 2024). "On the contrary, our results highlight the potential benefit for patients with NECTIN‐4 expression in their tumour tissue." (PMID 39072867, 2024). "Our next step involves validating the occurrence of autophagy in tumor cells following Nectin-4-MMAE treatment at the cellular level." (PMID 38664366, 2024). "ETx-22 ADC induced rapid and long-lasting tumor regression in various patient-derived xenograft models expressing low to high levels of nectin-4 and also in a monomethyl auristatin E–resistant xenograft model." (PMID 39440991, 2024). "Confirmatory immunohistochemistry demonstrated nectin-4 protein in tumor cells, with 61.4% having moderate or strong staining and 89.4% having >25% of tumor cells positive." (PMID 38893204, 2024). "When the average tumor volume approached 100 mm3, the treatment group received doses of 10 mg/kg, 5 mg/kg, and 2.5 mg/kg of Nectin-4 NDC." (PMID 38755613, 2024). "In the MC38 tumor-bearing mice expressing nectin-4, intravenous administration of BT7480 promoted CD8+ T cell tumor infiltration and induced complete tumor regression." (PMID 38298192, 2024). "This is because post-treatment SUVs can be influenced by other factors, such as baseline Nectin-4 expression variability or changes in the tumor microenvironment." (PMID 39763905, 2024). "Of eight NECTIN4-amplified PRIM with available matched MET, only one tumor lost NECTIN4 amplification during metastasis." (PMID 38657187, 2024). "To date, most research has focused on Nectin-4 as a transmembrane protein of tumor cells, with less attention paid to soluble Nectin-4." (PMID 38606099, 2024). "By day 3, however, an increase in [68Ga]AJ647 uptake was observed in the tumors of mice treated with the 6 mg/kg dose, suggesting that Nectin-4 became more accessible at this lower dose as the ADC cleared from the tumor." (PMID 39763905, 2024). "Nectin-4-targeted imaging also addresses the challenge of tumor heterogeneity in UC, where variable Nectin-4 expression impacts therapeutic outcomes." (PMID 39763905, 2024). "This has emphasized the value of Nectin-4 in tumor targeted therapy and promoted the implementation of more clinical trials of enfortumab vedotin." (PMID 38606099, 2024). "By contrast, PET imaging provided direct, tumor-specific insights into Nectin-4 engagement, enabling a more precise understanding of dose-exposure-response relationships." (PMID 39763905, 2024). "used spatial proteomics imaging to identify nectin-4+ tumor cells located within the tumor core and surrounded by CD137+ immune cell infiltration in non-small cell lung cancer, head and neck squamous cell carcinoma and bladder cancer." (PMID 38298192, 2024).
tumor (continued). "Nectin-4 is involved in tumor cell development, including adhesion, proliferation, migration, and angiogenesis, and it has prognostic significance in numerous cancers." (PMID 38606099, 2024). "The 15A7.5 antibody was selected on the basis of the differential binding to nectin-4 expressed on normal differentiated human primary keratinocytes and tumor cell lines." (PMID 39440991, 2024). "To gain a more comprehensive understanding of how tumor cells respond to Nectin-4-MMAE treatment, we conducted transcriptome RNA sequencing to assess changes in gene expression." (PMID 38664366, 2024). "Because of its high expression across multiple tumor types, Nectin-4 has emerged as an attractive target for the treatment of various cancers including NSCLC." (PMID 39337530, 2024). "The frequent occurrence of NECTIN4 amplifications in other cancer types suggests that this biomarker is a promising candidate with broader applicability for clinical development of NECTIN4-targeted ADCs in a tumor-agnostic context." (PMID 38657187, 2024). "This article reviews the diagnostic potential, prognostic significance, and molecular role of Nectin-4 in tumors, with a focus on clinical trials in the field of Nectin-4-related tumor treatment and the development of new drugs targeting Nectin-4." (PMID 38606099, 2024). "Nectin-4 is expressed in the urothelium and is primarily localized to the plasma membrane or cytoplasm of tumor cells." (PMID 39759708, 2024). "Both drugs use TLR8 agonists as payloads, with the difference that SBT6050 targets HER2 and SBT6290 targets Nectin4 (Nectin cell adhesion molecule 4, a type I membrane protein that is overexpressed in a variety of tumor cells)." (PMID 38298192, 2024). "Enfortumab is an antibody against a member of a family of adhesion proteins, nectins (nectin-4), exposed on the tumor surface." (PMID 39408784, 2024). "The results of our in vivo efficacy study, conducted on nude mice carrying NCI-N87 human tumor xenografts, indicate that the high dose (10 mg/kg) of Nectin-4 NDC achieved complete tumor regression, displaying a dose-dependent trend." (PMID 38755613, 2024). "PET imaging revealed dose-dependent variations in Nectin-4 engagement, with suboptimal EV doses resulting in incomplete Nectin-4 engagement and reduced tumor growth." (PMID 39763905, 2024). "BT8009 is a bicycle toxin conjugate consisting of a Nectin-4-targeting bicyclic peptide and cytotoxic payload that has demonstrated potent anti-tumor activity in rodent models." (PMID 39337530, 2024). "In 27 matched primary (PRIM) and corresponding metastatic (MET) tumor tissues, NECTIN4 CNV was stable in 93% (25 of 27)." (PMID 38657187, 2024). "At 3 h post-injection, substantial fluorescence of Nectin-4 NDC accumulated at the tumor location was observed." (PMID 38755613, 2024). "Analyzing the average radiant efficiency in the tumor region revealed that Nectin-4 NDC achieved peak accumulation at the tumor site at 3 h, followed by gradual clearance and significant enrichment." (PMID 38755613, 2024). "Binding to Nectin-4 adhesion immunoglobulin-like transmembrane molecules expressed on tumor cells, EV induces cell apoptosis." (PMID 39590140, 2024). "Tumor expression of targeted proteins such as Nectin-4 is vital for obtaining antitumor responses to antibody–drug conjugates, such as EV." (PMID 37174031, 2023). "More importantly, such self-clustering phenomenon was decreased by the treatment of both scFvs, indicating their ability to inhibit nectin-4-positive tumor cell aggregation." (PMID 38288120, 2023). "In a study of 99 patients with UTUC, Nectin-4 positivity was detected in 66% of the tumours examined by immunohistochemistry (IHC)." (PMID 38067262, 2023). "Next, we assessed the clinical relevance of Nectin-4 in archival tumor tissues from patients with EC (n = 320) and EIN (n = 54) and nonadjacent normal tissue (n = 87) using immunohistochemical staining." (PMID 37345201, 2023).